LAYN (layilin)
Diseases named in the same sentence as LAYN in open-access papers (continued):
Sharing a sentence is not in itself a finding about the gene and the disease.
tumor (continued). "Our research found that compared with high-dose anti-VEGFR2 combined with anti-PD-1, low-dose anti-VEGFR2 combined with anti-PD-1 down-regulated the expression of LAYN on tumor infiltrating exhausted CD8+T cells, increased the secretion of GZMB, and then enhanced the function of CD8+T cells." (PMID 36260222, 2022). "The results showed that in the low-dose anti-VEGFR2 antibody (DC101) group, the MFI of LAYN significantly decreased in tumor-infiltrating exhausted CD8+T cells, but the percentage of T cells treated by combination of different dosage of DC101 with anti-PD1 antibody in vitro didn’t change." (PMID 36260222, 2022). "Nevertheless, in hIgG1-G396R carriers, there were increased proportions of IgG+ plasma cells, CXCR5+ T follicular helper cells, CD6+ tumor-resident memory T cells, and decreased proportions of LAYN+ exhausted T cells, implying that the variant favors the formation of an antitumor microenvironment." (PMID 35133976, 2022). "Furthermore, we show that adhesion of MDA-MB-231 cells to bmMSC is facilitated by the tumor cell-induced HA-rich matrix and is mediated by the HA-receptor LAYN." (PMID 34707175, 2021). "Additionally, this mechanism fosters close cellular interaction between tumor cells and bmMSCs, which depends on the binding of the HA matrix to the HA receptor LAYN." (PMID 34707175, 2021). "Interestingly, a small subset of genes enriched in tumor Treg cells such as CTLA4, TIGIT, TNFRSF9, CD27, and LAYN are also highly expressed by exhausted tumor‐infiltrating CD8+ T cells reflecting a shared program of activation and exhaustion in these cells." (PMID 32272497, 2020). "Further studies need be done on whether LAYN is a crucial factor that mediating the DC and tumor metastasis." (PMID 30761122, 2019). "Thus, our study provides insights in understanding the potential role of LAYN in tumor immunology and its use as a cancer biomarker." (PMID 30761122, 2019). "Moreover, the correlation between LAYN expression and the marker genes of immune cells implicate the role of LAYN in regulating tumor immunology in COAD and STAD." (PMID 30761122, 2019). "It is possible that HA oligosaccharides are responsible for the increased activation of LAYN in these tumors and can potentially enhance the secretion of inflammatory factors which leads to the recruitment of more immune cells in the tumor microenvironment (TME)." (PMID 30761122, 2019). "However, subsequently, layilin has been found highly expressed on tumor-infiltrating cytotoxic CD8+ T-cells as well, particularly those with an exhaustive (highly expressing CTLA4, PDCD1, and HAVCR2) phenotype." (PMID 29887862, 2018). "In whole-tumor samples, overexpression of LAYN, MAGEH1, and CCR8, three of the most enriched genes in tumor-infiltrating Treg signature genes, was associated with a worse 5-year survival of CRC and NSCLC patients, pinpointing these genes as potential therapeutic targets." (PMID 29879107, 2018). "Taking CD4+ Treg cells and CD8+ cytotoxic T cells as examples, Treg cells derived from tumor tissues showed higher expression of LAYN, LGALS1 and TNFRSF1B, and cytotoxic T cells derived from tumor tissues showed higher expression of TNFRSF9 (encoding 4-1BB), LAYN and CTLA4." (PMID 36104333, 2022). "LAYN might be a potential target or a biomarker of patient response to tumor immunotherapy." (PMID 36260222, 2022). "However, the correlations of LAYN to prognosis and tumor-infiltrating lymphocytes in different cancers remain unclear." (PMID 30761122, 2019). "Together with talin, layilin supports LFA-1-mediated adhesiveness and the cytotoxic activity of CTLs, playing a critical role in promoting immune synapse formation and tumor cell killing, as demonstrated in melanoma." (PMID 39911389, 2025). "TMAO upregulates the expression of genes such as N-acetylneuraminyl-β-galactosidase, layilin, and serine protease high temperature requirement A serine peptidase 3, thereby modulating the HCC tumor microenvironment." (PMID 41395459, 2025).
tumor (continued). "First, the expression of genes associated with tumor-infiltrating Tregs such as CTLA4, GITR, LAYN and OX40 was significantly higher in tumor tissues compared to non-tumor tissues." (PMID 37313417, 2023). "Combining low-dose anti-VEGFR2 antibody with anti-PD1 antibody treatment resulted in a delay in tumor growth and extended the survival time of mice afflicted with tumors.VEGF-A upregulates both LAYN and immune receptors in human CD8+ T cells such as TIGIT." (PMID 37901223, 2023). "According to the current studies, there are 7 HA receptors, CD44, RHAMM, TLR2, TLR4, LYVE, LAYN and STAB2, which participate in connecting extracellular signal and intracellular signalling in tumor diseases." (PMID 36698043, 2023). "While comparing with normal Tregs, tumor Tregs had increased expression of multiple genes related with immune suppression, including DUSP4, IL2RA, TNFRSF4, LAYN and LGALS1." (PMID 35664061, 2022). "Unexpectedly, abundant of cytotoxic cells were observed in the adjacent tissues, while the T-cells exhaustion markers LAYN and CTLA4 were overexpressed in the tumor tissues." (PMID 35256589, 2022). "For the analysis, we have used expression levels of Layilin (LAYN), a potent maker for quantifying tumor-infiltrating exhausted CD8+ T cells." (PMID 35197510, 2022). "At the same time, how the activation of the downstream of LAYN affected other signal pathways, influencing the secretion of cytokines (such as IFN-γ, GZMB), and many other mechanisms that regulated anti-tumor immunity were worth of further investigation." (PMID 36260222, 2022). "Our study intended to identify how low-dose anti-angiogenic drugs affected the function of tumor-infiltrating CD8+T cells, and achieved better outcome by regulating expression of LAYN." (PMID 36260222, 2022). "LAYN+ Tregs showed highly expressed LAYN, TNFRSF9, and ICOS, but the proportion of this cell population in tumor‐infiltrating cells was very small, which was different from FOXP3+ Tregs." (PMID 35474948, 2022). "To identify the HA receptor that mediates binding of tumor cells to bmMSCs in our experimental setup, we next silenced the HA receptor genes CD44, RHAMM and LAYN by siRNA." (PMID 34707175, 2021). "The C4 subset was annotated as Treg cells based on the high expression signature genes of tumor-infiltrating Tregs (FOXP3, IL2RA, IL2RB, IL2RG, IL10RA, MAGEH1, LAYN, and GATA3)." (PMID 34663810, 2021). "HA oligosaccharides activation of LAYN can inhibit the E-cadherin protein expression, which is the crucial protein for epithelial-mesenchymal transformation (EMT) in tumor lymphatic metastasis." (PMID 30761122, 2019). "Enrichment of LAYN, MAGEH1, and CCR8 in whole tumor samples correlated significantly with reduced 5-year survival rate of CRC and NSCLC patients." (PMID 29887862, 2018). "Inhibition of both layilin and Stab2 suppresses tumor metastasis in animal models, while HA binding protein 1 (HABP1) promotes motility of melanoma cells and tumor growth." (PMID 24213471, 2012). "Interestingly, known markers of activated (TIGIT, LAYN and HAVCR2) and tumor-reactive T cells (ENTPD1) were segregated into different clusters." (PMID 38724668, 2025). "Importantly, the T‐cell exhaustion biomarkers (LAYN, CTLA4, and HAVCR2) were highly expressed in the tumor tissues." (PMID 38204220, 2024). "Another finding of this study was the correlation between LAYN and several immune checkpoint markers in LIHC, suggesting that tumor immune escape might be involved in LAYN-mediated tumorigenesis in LIHC." (PMID 36398067, 2022). "We also performed double immunofluorescence staining of LAYN and CD8 on tumor tissue samples." (PMID 36260222, 2022). "Furthermore, the overexpression of LAYN on CD8+ T cells in human blood leads to a significant reduction in the production of IFN-g, which is a key cytokine involved in the tumor-killing activity, and supports LAYN as a negative regulator." (PMID 36466840, 2022).
tumor (continued). "Notably, layilin exhibits a distinct preference for binding LMW-HA (< 70 kDa), suggesting that it is a specialized sensor of tissue inflammation and a key mediator of immune responses in the tumor microenvironment (TME)." (PMID 41404063, 2025). "In this study, the impact of the tumor immune microenvironment (TIME) on specific gene expression (LAYN, MAGEH1, and CCR8) in tumor-infiltrating Tregs cells was confirmed, and these gene expressions were found to be correlated with immune therapy response, tumor-suppressive activity, and prognosis." (PMID 38077354, 2023). "LAYN, which was reported as a novel exhausted marker in our previous study, underwent striking methylation during naïve to TEM differentiation, maintained this methylation status in both bystander subtypes, and acquired demethylation in tumor-reactive T cells." (PMID 31892342, 2019). "Therefore, we selected the cancer types in which LAYN expression levels have a significant negative correlation with tumor purity in TIMER and a significant correlation with prognosis in GEPIA." (PMID 30761122, 2019). "We found that besides TNFRSF4, Treg functional signature genes such as FoxP3, CTLA4, TIGIT, TNFRSF18 (GIRT), CCR8, LAYN, and MAGEH1 were also overexpressed in C11-Tregs-FoxP3 of treatment-naive and non-MPR tumor lesions, but not for MPR tumor lesions." (PMID 35831283, 2022). "Along with these genes whose function in Treg cells have previously been characterized, several other genes such as LAYN, CD177, IGFLR1, and IL1R2 that are not well studied are also up‐regulated in tumor Treg cells." (PMID 32272497, 2020).
cancer (29 papers, 2019 to 2025). A tumor composed of atypical neoplastic, often pleomorphic cells that invade other tissues. "Given the association of LAYN expression with immune infiltration level in diverse types of cancer, we next determined the distinct types of cancers in which LAYN was associated with prognosis and immune infiltration." (PMID 30761122, 2019). "TCGA data showed that high LAYN levels were associated with short survival time of various cancers." (PMID 36466840, 2022). "The apparent contradictions in the functions of layilin highlight the complexity of its roles and underscore the need for systematic investigations to fully explain its therapeutic potential in cancer settings." (PMID 41404063, 2025). "In UCEC and a few other cancers, LAYN expression showed a variation in its correlation with different immune cells." (PMID 40076932, 2025). "The mRNA expression profile of six Tex markers, LAG-3, PDCD1, TIGIT, HAVCR2, CXCL13, and LAYN was investigated in pan-cancer." (PMID 40076932, 2025). "Some upregulated genes of this study were previously identified as potential targets for cancer therapeutics (LAYN, IGFLR1)." (PMID 39052598, 2024). "Trend analysis also showed differences in LAYN expression between pathological and clinical stages in various cancers, such as LUSC and BRCA." (PMID 39064019, 2024). "Relevant studies had shown that LAYN was also expressed in TILs isolated from several human cancers." (PMID 36260222, 2022). "To understand the potential role of LAYN in tumorigenesis, we first evaluated the expression level of LAYN in human cancers using the UALCAN database." (PMID 36398067, 2022). "In this present study, we comprehensively analyzed LAYN expression and correlation with prognosis of cancer patients in databases such as Oncomine, PrognoScan, and Kaplan-Meier plotter." (PMID 30761122, 2019). "We assessed the correlations of LAYN expression with immune infiltration levels in 39 cancer types from TIMER." (PMID 30761122, 2019). "To further evaluate LAYN expression in human cancers, we examined LAYN expression using the RNA-seq data of multiple malignancies in TCGA." (PMID 30761122, 2019). "Here, we report that variations in LAYN expression level correlate to prognosis in different types of cancer." (PMID 30761122, 2019). "The differential expression of LAYN between cancer and normal tissues was observed in many types of cancers." (PMID 30761122, 2019). "In this study, we examined the expression levels of LAYN and systematic prognostic landscape in different types of cancers using independent datasets in Oncomine and 33 type cancers of TCGA data in GEPIA." (PMID 30761122, 2019). "Notably, LAYN represents a valuable prognostic biomarker across various cancer types and also serves as an indicator of dysfunctional or exhausted T cells." (PMID 40452847, 2025). "In the present study, we first visualized the expression landscape of LAYN in pan-cancer." (PMID 38430385, 2024). "To this end, we explored the mutation rate of the Tex signature genes in pan-cancer, and we observed a 2–3% SNV mutation frequency of PDCD1, LAG3, TIGIT, HAVCR2, and LAYN mainly in UCEC and SKCM, with HAVCR2 and TIGIT having the highest mutation frequencies (24% and 23% of samples, respectively)." (PMID 39064019, 2024). "Previous studies suggested that LAYN is involved in cancer cell invasion and could serve as a prognostic biomarker in human cancers." (PMID 36398067, 2022). "Moreover, the expression of IL2, IL10, IL12, LAYN in pre-exhausted T cells were consistent with the expression of genes in other cancer, suggesting that pre-exhausted T cell have common features in immune microenvironment." (PMID 34434188, 2021). "Layilin plays important roles in cell migration and membrane ruffling as demonstrated by layilin knockdown inhibiting cell migration in vitro, and inhibiting cancer cell metastases in vivo." (PMID 32411124, 2020).
cancer (continued). "Furthermore, our analyses show that in colon and gastic cancers immune infiltration levels and diverse immune marker sets are correlated with levels of LAYN expression." (PMID 30761122, 2019). "We analyzed relationships between LAYN expression and prognostic values in 33 types of cancer." (PMID 30761122, 2019). "Moreover, LAYN significantly impacts the prognosis of diverse cancers via The Cancer Genome Atlas (TCGA)." (PMID 30761122, 2019). "The discrepancies in levels of LAYN expression in different cancer types in different databases may be a reflection in data collection approaches and underlying mechanisms pertinent to different biological properties." (PMID 30761122, 2019). "Finally, we gathered the IC50 of a wide variety of drugs among different cancer cell lines through the GDSC and CTRP databases and tried to explore the possible associations with the corresponding CXCL13, HAVCR2, LAG3, TIGIT, PDCD1, and LAYN mRNA values." (PMID 39064019, 2024). "In addition to microarray analysis of LAYN in the PrognoScan and Kaplan-Meier plotter databases, the RNA sequencing data in TCGA were also used to analyze the prognostic potential of LAYN in different cancers via GEPIA." (PMID 30761122, 2019). "We investigated whether LAYN expression was correlated with prognosis in cancer patients." (PMID 30761122, 2019). "Therefore, we investigated whether LAYN expression was correlated with immune infiltration levels in different types of cancer." (PMID 30761122, 2019). "Previous studies have highlighted the differential expression patterns of HAVCR2, TIGIT, LAG3, LAYN, and CXCL13, showing strong correlations with survival outcomes across multiple cancer types." (PMID 40076932, 2025). "KEGG pathway analysis suggested that LAYN co-expression network was mainly enriched in ECM receptor interaction, adhesive plaque, PI3K-Akt signaling pathway, HPV infection, and cancer-related pathways." (PMID 38430385, 2024). "We investigated the methylation levels (beta values) of TIGIT, CXCL13, LAYN, LAG3, PDCD1, and HAVCR2 across different cancer types." (PMID 39064019, 2024). "We initially explored the expression of the Tex signature genes (LAG3, TIGIT, LAYN, PDCD1, HAVCR2, and CXCL13) in pan-cancer." (PMID 39064019, 2024). "Layilin (LAYN), which contains homology with C-type lectins, plays a critical role in tumorigenesis and cancer progression." (PMID 38430385, 2024). "Accordingly, high LAYN expression belongs to transcriptomic signatures specific for regulatory T cells (Tregs) and exhausted CD8+ T cells for several cancer types including breast cancer." (PMID 37996402, 2023). "However, each gene in different cancers positively correlated (p < 0.05) with either its mRNA expression or CNVs, e.g., TIGIT in ACC, LAG3 in UVM, HAVCR2 in LUSC, LAYN in OV and PDCD1 in BLCA." (PMID 40076932, 2025). "We also highlight high LAYN methylation in most tumors and a negative correlation between methylation levels and immune cell infiltration in various cancers." (PMID 39064019, 2024). "In addition, LAYN expression has significant correlations with infiltrating levels of CD8+ T cells in 18 types of cancer, CD4+ T cells in 23 types of cancer, macrophages in 23 types of cancer, neutrophils in 19 types of cancer, and dendritic cells in 25 types of cancer." (PMID 30761122, 2019). "It was identified that HAVCR2 had positive infiltration scores in all cancer types, whereas a negative infiltration score was noted for CXCL13 (in LGG and DLBCL), LAG3 (in DLBCL and AML), LAYN (in CHOL, KICH, AML, LGG, PCPG, THCA and UCS), PDCD1 (in DLBCL, AML and THYM) and TIGIT (DLBCL and AML)." (PMID 40076932, 2025). "LAYN expression did not reveal much inducing effect on apoptosis (3%) but had a potentially strong activating effect on EMT (38%), hormone ER (16%), RASMAPK (12%), RTK (12%), hormone AR (6%) and TSCmTOR (6%) pathways, in pan-cancer." (PMID 40076932, 2025).
head and neck tumors (1 paper, 2024). "Through forest plot, we found that among common head and neck tumors, the expression of LAYN was only correlated with the survival of the base of tongue cancer patients with statistical difference (HR = 1.11, 95% CI 1.01–1.21, P < 0.05)." (PMID 38430385, 2024).
inflammation (1 paper, 2024). Aberrant reaction of the microcirculation characterized by movement of fluid and leukocytes from the blood into extravascular tissues. "Common upregulated genes were e.g. important for T cell immunobiology (ARG2, SLC43A2, IGFLR1), involved in cell migration (LAYN) or known to be involved in cigarette smoke-induced pulmonary inflammation and autophagy in mice (EPHX2)." (PMID 39052598, 2024).
LAYN also shares sentences with these, for which no sentence is quoted: prostate carcinoma (4 papers); bladder urothelial cancer (2); kidney chromophobe (2); aortic stenosis (1); atopic dermatitis (1); brain cancer (1); breast invasive carcinoma (1); colon adenocarcinoma (1); COVID-19 (1); delirium (1); demyelination (1); endometrial cancer (1); glioma (1); head and neck cancer (1); IgA nephropathy (1); leukemia (1); low grade glioma (1); lymph node metastasis (1); Lymphatic Metastasis (1); lymphoma (1); mesothelioma (1); multiple myeloma (1); neuropathies (1); ovarian serous cystadenocarcinoma (1); pregnancy disorder (1); prostate adenocarcinoma (1); rectum adenocarcinoma (1); renal clear cell carcinoma (1); renal disease (1); rheumatic disease (1).
A further 6 diseases each share a sentence with LAYN in 1 paper.